XIST (X inactive specific transcript)
Diseases named in the same sentence as XIST in open-access papers (continued):
Sharing a sentence is not in itself a finding about the gene and the disease.
prostate carcinoma (continued). "Function assays suggested that overexpression of XIST inhibited proliferation, migration and invasion in prostate cancer cells in vitro and in vivo." (PMID 29212233, 2017). "In the present study, we confirmed that down-regulation of XIST is a characteristic molecular change in prostate cancer, and the expression of XIST is negatively correlated with clinical stage, metastasis and Gleason score." (PMID 29212233, 2017). "However, the underlying mechanism of XIST in prostate cancer remains unclear." (PMID 29212233, 2017). "Taken together, our study indicated that lncRNA XIST acts as a tumor suppressor in prostate cancer, and this regulatory effect of XIST will shed new light on epigenetic diagnostics and therapeutics in prostate cancer." (PMID 29212233, 2017). "To investigate the biological functions of lncRNA XIST in prostate cancer cells, we increased expression of XIST in DU145 cells by transfection of recombinant adenoviruses and suppressed that in LNCAP cells by small interfering RNA (siRNA)." (PMID 29212233, 2017). "Low XIST expression levels were also correlated with high Gleason score, clinical stage and metastasis in patients with prostate cancer." (PMID 29212233, 2017). "Together, our work provides a new prospect in comprehending the role of lncRNA XIST in prostate cancer, and the regulatory effect of lncRNA XIST will shed new light on molecular diagnostics and therapeutics in prostate cancer." (PMID 29212233, 2017). "Then, we determined the expression of XIST in prostate cancer specimens and adjacent normal tissues from 62 prostate cancer patients by qRT-PCR." (PMID 29212233, 2017). "Low expression of XIST was correlated with poor prognosis and advanced tumor stage in prostate cancer patients." (PMID 29212233, 2017). "Finally, we discovered that XIST expression levels differed significantly in patients with different prostate cancer prognoses; the higher the expression level of XIST, the poorer the prognosis of the patients." (PMID 36038831, 2022). "This may be due to increased levels of demethylation of the XIST 5ˊ region in patients with prostate cancer, resulting in the increased expression level of XIST." (PMID 36038831, 2022). "Furthermore, the overexpression of XIST has the potential to inhibit proliferation, migration, and invasion in prostate cancer cells." (PMID 34944867, 2021). "Additionally, we determined that lncRNA XIST positively regulated RKIP expression at post-transcription level by targeting miR-23a in prostate cancer." (PMID 29212233, 2017). "Collectively, these data suggest that XIST may be involved in the occurrence and development of prostate cancer." (PMID 29212233, 2017). "The results revealed that XIST expression was significantly down-regulated in prostate cancer tissues compared to normal tissues and negatively correlated with the metastasis of prostate cancer." (PMID 29212233, 2017). "In the present study, we verified that XIST could positively regulate the expression of RKIP post-transcriptionally through sponging miR-23a in prostate cancer cells." (PMID 29212233, 2017). "We then investigated whether XIST expression is correlated with the overall survival time in prostate cancer patients." (PMID 29212233, 2017). "Therefore, our study indicated that lncRNA XIST has a potential to be applied as a novel therapeutic target into the treatment of prostate cancer." (PMID 29212233, 2017). "Low expression of XIST may lead to poor prognosis in prostate cancer patients." (PMID 29212233, 2017). "Therefore, we asked whether lncRNA XIST has a similar function in prostate cancer." (PMID 29212233, 2017). "In addition, we investigated the expression of XIST in the normal human prostate epithelial cell line RWPE1 and 3 types of human prostate cancer cell lines (PC3, DU145 and LNCAP)." (PMID 29212233, 2017).
prostate carcinoma (continued). "In the present study, we found that the expression of XIST in prostate cancer tissues was remarkably decreased compared with adjacent normal tissues." (PMID 29212233, 2017). "Our study found that XIST may not predict whether patients will develop prostate cancer but is highly expressed in PCa and its expression is related to patient prognosis." (PMID 36038831, 2022).
Sepsis (13 papers, 2019 to 2026). Sepsis is defined as life-threatening organ dysfunction caused by a dysregulated host response to infection. "XIST inhibition was also described to mitigate sepsis-induced acute liver injury by suppressing Bromodomain-containing Protein 4 (BRD4) expression." (PMID 39198331, 2024). "Studies have shown that silencing or downregulation of XIST expression protects against sepsis-induced multiorgan dysfunction." (PMID 36188533, 2022). "Among the upstream lncRNAs of hsa-let-7b-5p, only XIST has been found to be involved in sepsis regulation." (PMID 36188533, 2022). "Downregulation of XIST reduced inflammation, oxidative stress, and apoptosis in sepsis-induced acute liver injury." (PMID 34956235, 2021). "Up-regulation of XIST increased viability and inhibited inflammatory response and apoptosis in sepsis-induced ALI." (PMID 34956235, 2021). "Several lncRNAs, including LINC00472, nuclear enriched abundant transcript 1 (NEAT1), colorectal neoplasia differentially expressed, and X‐inactive‐specific transcript (XIST), have been reported to participate in liver damage induced by sepsis through modulating the inflammatory response." (PMID 37829506, 2023). "For example, NEAT1 was reported to promote the inflammatory response by regulating the Let‐7a/TLR4 axis in sepsis‐induced liver injury, whereas silencing the lncRNA XIST protected against sepsis‐induced acute liver injury through the inhibition of bromodomain‐containing protein 4 expression." (PMID 37829506, 2023). "Up-regulation of XIST enhanced apoptosis in sepsis-induced AKI." (PMID 34956235, 2021). "The XIST/miR-150-5p/Fos pathway has also been shown to impact sepsis-induced myocardial damage." (PMID 34743709, 2021). "X inactive specific transcript (XIST) was observed to be overexpressed in a lung injury rat model, and the researchers concluded that XIST might ameliorate sepsis-induced lung injury by modulating miR-16-5p." (PMID 34630395, 2021). "A total of 1389 DEGs such as NOV, SEPT9, XIST, ESYT1 were upregulated in sepsis, whereas 1657 DEGs such as S100A9, IRAK3, MCEMP1, TLR5, CD177 were downregulated." (PMID 41542228, 2026). "NEAT1, MALAT1, THRIL, XIST, MIAT and TUG1 are among lncRNAs that participate in the pathoetiology of sepsis-related complications." (PMID 34956235, 2021). "Among them, miR-29b-3p, miR-15b-5p, miR-15a-5p, miR-107, XIST, miR-19a-3p, miR-16-5p, miR-19b-3p, miR-92a-3p, and CUL3 were closely related to the pathogenesis of sepsis-induced AKI." (PMID 31658856, 2019). "Aberrant expression of XIST also promotes inflammatory responses during tissue injury such as cerebral ischemia/reperfusion injury, lipopolysaccharide (LPS)-induced acute lung injury (ALI), and sepsis-induced acute liver injury." (PMID 36922677, 2023). "lncRNA XIST targets miR-155-5p and upregulates WWC1 to dampen inflammatory cytokine generation and cell apoptosis, hence attenuating acute kidney injury induced by sepsis." (PMID 36333771, 2022).
Autoimmunity (12 papers, 2019 to 2025). The occurrence of an immune reaction against the organism's own cells or tissues. "Male mice engineered to overexpress transgenic XIST are prone to autoimmunity, developing severe multiorgan pathology after transgenic XIST induction as well as autoantibodies against XIST–RNP complexes." (PMID 40741215, 2025). "Recent discoveries have identified important potential roles for the lncRNA XIST in autoimmunity, further implicating XCI as a driver of this sex bias." (PMID 40741215, 2025). "In females, XIST attenuates inflammatory response, and its dysregulation in B or T cells contributes to female-biased autoimmunity." (PMID 39623319, 2024). "The lncRNA XIST, which drives XCI, has been linked to female-biased autoimmunity and immune responses by regulating different immune cell populations." (PMID 38949020, 2024). "An alternative hypothesis for the role of XIST in sex-biased autoimmunity is that XIST-containing ribonucleoprotein (RNP) complexes are immunogenic and promote autoimmunity." (PMID 40741215, 2025). "Interestingly, we also detected increased expression of the long noncoding RNA XIST, which has been recently described to contribute to inflammatory responses that potentially drive female-biased autoimmunity." (PMID 41174786, 2025). "Interestingly, far from its function in X chromosome inactivation (XCI), both studies suggest that XIST rather induces autoimmunity by activating innate or adaptive immune responses." (PMID 38665922, 2024). "Consistent with this, misregulation of Xist/XIST RNA is also observed in autoimmunity." (PMID 39471841, 2024). "al., hypothesized that XIST may promote female-biased autoimmunity by serving as an autoantigen carrier." (PMID 38665922, 2024). "The disease, however, was only induced in autoimmune prone male SJL/J mice but not in C57BL/6J male mice, implying that XIST overexpression alone is insufficient to promote autoimmunity in this experimental model." (PMID 38665922, 2024).
nasopharyngeal carcinoma (12 papers, 2018 to 2024). A carcinoma arising from the nasopharyngeal epithelium. "For example, XIST was involved in cancer metastasis and development through targeting miR-34a-5p in human nasopharyngeal carcinoma." (PMID 32066502, 2020). "In nasopharyngeal carcinoma, XIST expression levels could differentiate tumoral tissues from nearby non-cancerous samples with diagnostic power of 0.813." (PMID 34179019, 2021). "In nasopharyngeal carcinoma (NPC), targeting XIST inhibited NPC cell proliferation and invasion in vitro and NPC tumor growth in vivo." (PMID 31189404, 2019).
atherosclerosis (11 papers, 2017 to 2026). A disease characterized by the build-up of fatty material and calcium deposition in the arterial wall resulting in partial or complete occlusion of the arterial lumen. "Dysregulation of XIST is closely associated with atherosclerosis, hypertrophic cardiomyopathy and myocardial fibrosis." (PMID 40342975, 2025). "A loop of has-circ-0028198/has-circ-0092317/XIST/miR-543/aspartate beta-hydroxylase or has-circ-0028198/has-circ-0092317/XIST/miR-543/phosphodiesterase 3B has been implicated in oxidized, low-density, lipoprotein-stimulated foam cells in atherosclerosis." (PMID 32293498, 2020). "Previous studies have highlighted the significant roles of NEAT1 and XIST in the progression of atherosclerosis and CHD." (PMID 41614904, 2026). "Specifically, survival was shorter in patients with atherosclerosis who had lower XIST and SNHG5 levels." (PMID 40032652, 2025). "In conclusion, our study findings show that XIST inhibition can inhibit the proliferation and migration of atherosclerosis vascular smooth muscle cells, which provides a new theoretical basis for atherosclerosis treatment." (PMID 35028010, 2022). "Based on the results, we concluded that XIST regulates the progression of atherosclerosis through the miR-539-5p/SPP1 axis." (PMID 35028010, 2022). "The viability of HUVECs was improved upon XIST knockdown under oxidative low-density lipoprotein treatment in atherosclerosis." (PMID 36474713, 2022). "The role of lncRNA XIST in the proliferation and infiltration of VSMCs in atherosclerosis is still not fully understood, and further research is required to understand this process." (PMID 35028010, 2022). "First, we interfered with the XIST expression in atherosclerotic mice (AS) through the sh-RNA of XIST to determine the role of XIST in the process of atherosclerosis." (PMID 35028010, 2022). "The apoptosis of HUVECs was inhibited by lncRNA XIST knockdown via miR-30c-5p/PTEN axis in atherosclerosis." (PMID 36474713, 2022). "XIST expression is also found to be up-regulated in human umbilical vein endothelial cells treated by oxidized low-density lipoprotein during atherosclerosis." (PMID 33228517, 2020). "This suggests that XIST promotes the AP formation in mice with atherosclerosis." (PMID 35028010, 2022). "Little is known about the biological role and mechanism of XIST in atherosclerosis." (PMID 35028010, 2022). "However, the aortic plaques of the AS + sh-XIST group had a higher collagen content than that of the AS group, suggesting that XIST reduces the collagen content of aortic plaques in mice with atherosclerosis." (PMID 35028010, 2022). "Nevertheless, the regulatory mechanism of XIST was unidentified in atherosclerosis." (PMID 33542956, 2021). "A further study found that serum XIST and SNHG5 levels were lower and the miR‐155 level was higher in patients with atherosclerosis than in controls." (PMID 40032652, 2025). "However, the biological role and mechanism of XIST in atherosclerosis remain unclear." (PMID 35028010, 2022). "To further investigate the role of XIST in atherosclerosis, we used ox-LDL treatment of a human vascular smooth muscle cell line, VSMC, which has been widely used for in vitro studies of atherosclerosis." (PMID 35028010, 2022). "In this study, we aimed to further explore the potential roles and their accompanying molecular basis of XIST in the process of VSMC proliferation and infiltration to discover potential therapeutic targets for atherosclerosis." (PMID 35028010, 2022). "What is more, the knockdown of lncRNA XIST could reduce the vascular wall injury induced by low-density lipoprotein via miR-204-5p/toll-like receptor 4 (TLR4), which attenuated atherosclerosis." (PMID 36474713, 2022). "Mechanistically, XIST could regulate PAPPA expression in ox-LDL-induced HUVECs by sponging miR-98-5p, providing understanding for atherosclerosis." (PMID 33542956, 2021).
atherosclerosis (continued). "Functional experiments provided insight into the function of the XIST/miR-98-5p/PAPPA axis in ox-LDL-mediated proliferation, apoptosis, and inflammatory response of HUVECs, which may imply a new molecular biomarker for atherosclerosis." (PMID 33542956, 2021). "Multivariate analyses further identified low XIST/SNHG5 expression, a high miR‐155 level, severe stenosis, and elevated triglycerides, low‐density lipoprotein cholesterol, and high‐sensitivity C‐reactive protein to be independent predictors of a poor prognosis in patients with atherosclerosis." (PMID 40032652, 2025). "We also focused on discovering the possible role and mechanism of lncRNA XIST in oxidized low-density lipoprotein- (ox-LDL-) stimulated vascular smooth muscle cells (VSMCs), which could further help evalute its possible a role in the progression of atherosclerosis." (PMID 35028010, 2022).
melanoma (11 papers, 2019 to 2025). A malignant, usually aggressive tumor composed of atypical, neoplastic melanocytes. "Furthermore, the results of our multivariate Cox analysis suggested that the combination of DTL, LINC00520, ZSCAN16-AS1, XIST, and let-7a-5p could identify high-risk melanoma patients." (PMID 33854593, 2021). "To date, in vitro studies conducted on A375 melanoma cells have revealed overexpression of XIST and a positive effect of lncRNA in question on cell proliferation and viability, as well as promotion of oncogenesis." (PMID 38601651, 2024). "The results showed that compared with normal nevus tissues, LINC00520, ZSCAN16-AS1, MMP9, and DTL had higher expression in melanoma, whereas XIST had lower expression." (PMID 33854593, 2021). "In the current study, we found that DTL, MMP9, LINC00520, and ZSCAN16-AS1 were highly expressed in melanoma compared with normal melanocytes, whereas XIST and let-7a-5p showed the opposite trend." (PMID 33854593, 2021). "Recently, the upregulated expression of X-inactive-specific transcript (XIST) in MM tissues and resistant cell lines was reported, with XIST being proposed as a crucial regulator in melanoma progression." (PMID 33203119, 2020). "However, previous studies showed that XIST was highly expressed in melanoma, contrary to our results." (PMID 33854593, 2021). "Overexpression of XIST can promote the proliferation, migration, and invasion of melanoma cells." (PMID 33854593, 2021). "XIST is an important regulator of progression and oxaliplatin-resistance in malignant melanoma." (PMID 32591022, 2020). "Moreover, XIST is associated with TNM stage and lymphatic metastasis in patients with melanoma." (PMID 33854593, 2021). "Functional studies concerning XIST repressed PI3KR1 and AKT expression, leading to inhibition of melanoma cell proliferation and migration, at the same time increasing sensitivity to oxaliplatin." (PMID 33203119, 2020). "Finally, five predictive genes, ZSCAN16-AS1, LINC00520, XIST, DTL, and let-7a-5p were identified; these genes are closely related to the occurrence of melanoma." (PMID 33854593, 2021). "The role of XIST in melanoma has not been fully elucidated; we will investigate this in future research." (PMID 33854593, 2021).
breast tumor (10 papers, 2014 to 2024). "Expressions of exo‐XIST were markedly decreased after resection of the primary breast tumours, and obviously increased at the time of recurrence." (PMID 33949761, 2021). "In contrast, XIST is a downregulated lncRNA found in breast tumor samples and other cancer cell lines that acts as a tumor suppressor." (PMID 29719633, 2018). "Interestingly, it has been observed that serum exo‐XIST levels markedly decreased after resection of the primary breast tumours." (PMID 33949761, 2021). "The XIST RNA domain number in BRCA1 breast tumor was associated with chromosomal genetic abnormalities, and XIST might become a predictive biomarker for prognosis of patients with BRCA1 breast tumor." (PMID 36212008, 2022). "Aberrant expression of XIST is found in some breast tumours, but the role of XIST in this disease had not been characterised." (PMID 37801168, 2023).
retinoblastoma (10 papers, 2019 to 2023). A malignant tumor that originates in the nuclear layer of the retina. "Herein, the present study is aimed at delving into how XIST functions in retinoblastoma (RB) and investigating its underlying mechanism." (PMID 33942699, 2021). "LnRNA XIST expression is increased in retinoblastoma, with a higher LC3B‐II/I ratio and lower p62 expression in tumour cells, indicating activated autophagy." (PMID 37837401, 2023). "In retinoblastoma, XIST is highly expressed, and silencing XIST attenuates cell proliferation and autophagy, thereby enhancing the sensitivity to VCR." (PMID 37837401, 2023). "It has been reported that XIST was involved in the epithelial-mesenchymal transitions of retinoblastoma and also participated in the apoptosis and migration of retinal pigment epithelial cells subjected to hyperglycemia." (PMID 35461232, 2022). "For example, the lncRNA XIST promotes the epithelial to mesenchymal transition of retinoblastoma via sponging miR-101." (PMID 31019967, 2019). "XIST knockdown weakens the proliferation and autophagy in retinoblastoma cells." (PMID 36908288, 2023). "Another study in retinoblastoma (RB) showed that XIST supports proliferation, migration, invasion through the accomplishment of the EMT program and the blocking of apoptosis." (PMID 31003545, 2019). "XIST, by sponging/antagonizing miR-124, a STAT3 targeting miRNA, enhances STAT3 expression in retinoblastoma." (PMID 36922677, 2023).